PDCD4 (programmed cell death 4)
Diseases named in the same sentence as PDCD4 in open-access papers (continued):
Sharing a sentence is not in itself a finding about the gene and the disease.
Sepsis (6 papers, 2014 to 2023). Sepsis is defined as life-threatening organ dysfunction caused by a dysregulated host response to infection. "PDCD4 promotes sepsis through activation of the NF-κB pathway and inhibition of IL-10 production." (PMID 38132140, 2023). "believed that MSC-derived EV miR-21 could induce M2 macrophage polarization by inhibiting programmed cell death 4(PDCD4), thereby alleviating sepsis." (PMID 35769456, 2022). "Moreover, as total PDCD4 is rapidly degraded upon its release from eIF4A, the lack of a detectable change in total PDCD4 suggests an alteration in eIF4A helicase activity is an unlikely mechanism for the sepsis-induced reduction in protein synthesis in the presence of normal eIF4E•eIF4G binding." (PMID 24945486, 2014). "Moreover, the significant up-regulation of miR-21 in MSC-EVs caused by IL-1β can induce the M2 polarization of macrophages by inhibiting the effect of programmed cell death 4 (PDCD4), with similar pattern as miRNA-146a in sepsis." (PMID 35463634, 2022). "The total amount PDCD4 was not altered in DKO mice or in response to sepsis." (PMID 24945486, 2014).
acute myeloid leukemia (5 papers, 2009 to 2025). Acute myeloid leukemia (AML) is a group of neoplasms arising from precursor cells committed to the myeloid cell-line differentiation. "Finally, we show that the use of PDCD4-derived peptides to block the interaction between NPMc+ and PDCD4 exhibits a promising therapeutic effect in NPM1-mutated acute myeloid leukemia (AML) mice." (PMID 41234771, 2025). "A study on a human acute myeloid leukemia (AML) cell line NB4 demonstrated that Knockdown of PDCD4 by RNA interference (siRNA) leads to induction of c-myc, suggesting that c-myc maybe a potential down-stream target of PDCD4." (PMID 19480673, 2009). "The phosphoSTAT5 — miR-21 — PDCD4 pathway was active in CML primary CD34+ cells, but also in acute myeloid leukemia (AML) models like MV4.11 and MOLM13, where the constitutively active tyrosine kinase FLT3-ITD plays a similar role to BCR-ABL1 in the K562 cell line." (PMID 29100302, 2017). "In acute myeloid leukemia (AML) cell, ectopic transfection of synthetic miR-29b can up-regulate the pro-apoptotic genes, such as BIM (BCL2L11) and the tumor suppressor programmed cell death-4 (PDCD4)." (PMID 27391030, 2016).
Cerebral ischemia (5 papers, 2017 to 2025). Restriction of arterial blood supply to the brain associated with insufficient oxygenation to support the metabolic requirements of the tissue. "Its neuroprotective role has been highlighted in studies showing that miR-499a-5p attenuates cerebral ischemia/reperfusion injury by targeting PDCD4." (PMID 40004152, 2025). "The pro-apoptotic factor ‘programmed cell death 4’ (PDCD4) was found to be increased in an undifferentiated SH-SY5Y cell model of cerebral ischemia." (PMID 37380886, 2023). "In line with our findings, previous reports indicate that miR-21 attenuates inflammatory responses in retinal I/R through PDCD4 or TLR4-dependent mechanisms, and in brain ischemia fosters M2 polarization of microglia with concomitant neuroprotection by engaging the PI3K/AKT signaling axis." (PMID 41153739, 2025).
colitis (5 papers, 2017 to 2023). Inflammation of the colon. "Moreover, PDCD4 deficiency in mouse models aggravates colitis and colitis-associated CRC by promoting the IL-6/STAT3 pathway." (PMID 34771727, 2021). "This suppression is also seen in dextran sodium sulphate (DSS) induced colitis in mice, where inflammation decreases PDCD4 protein expression." (PMID 35847932, 2022). "Targeting oncomiRs such as miR-21 and miR-181-b, and lack of PDCD4 in colitis and CAC mice models have been associated with enhanced IL-6 production, intensified activity of STAT3 signaling pathway, enhanced colitis and proliferation of tumor cells." (PMID 35410210, 2022). "In addition, MiRNA-21-/- knockout mice, given azoxymethane and dextran sodium sulphate (DSS) to induce colitis-associated CRC, had decreased inflammatory cytokines, reduced tumour size and tumour number and increased PDCD4 expression compared to control wild-type animals." (PMID 35847932, 2022).
depression (5 papers, 2021 to 2025). "The PCD gene Pdcd4 has been implicated in depression by specifically inhibiting proteins associated with neuronal function, thus promoting the progression of depressive symptoms." (PMID 40370590, 2025). "We next explored the mechanism underlying microglial Pdcd4 deficiency-induced antidepressant effect in neuroinflammation-associated depression." (PMID 38822367, 2024). "Herein, we provided strong evidence that Pdcd4 deficiency conferred resilience to CRS-induced depression-like behaviors in mice via increasing mTORC1-regulated BDNF protein level and maintaining of synaptic plasticity in the hippocampus." (PMID 32203159, 2021). "Altogether, these data suggest that Pdcd4 deficiency in mice show resistance to CRS-induced depression- and anxiety-like behaviors." (PMID 32203159, 2021). "Further exploration is needed to determine whether Pdcd4 plays a role in mitochondria function, which is implicated in cell metabolism and may contribute to the development of depression." (PMID 38822367, 2024). "Next, we investigated whether the enhanced Pdcd4 expression could mimic the increased depression- and anxiety-like behaviors caused by CRS under physiological conditions." (PMID 32203159, 2021). "However, the specific mechanism underlying Pdcd4-regulated neuroinflammation in depression is still unknown." (PMID 38822367, 2024). "Suppressing Pdcd4 expression has been shown to alleviate these symptoms, with recent studies providing direct evidence that targeting Pdcd4 can improve depression outcomes." (PMID 40370590, 2025). "Our study elucidates the distinct involvement of microglial Pdcd4 in neuroinflammation, suggesting its potential as a therapeutic target for neuroinflammation-related depression." (PMID 38822367, 2024). "Our previous reports have demonstrated Pdcd4 is elevated in brain of patient with depression, and neuronal-expressed Pdcd4 is involved in stress-induced depressive-like behaviors, by blocking BDNF and up-regulating proinflammatory response." (PMID 38822367, 2024). "Firstly, we analyzed the silencing effect of RVG/siPdcd4 treatment on Pdcd4 expression in depression related regions by RT-PCR." (PMID 34772918, 2021). "Overall, these data indicate that blockage of the association between Pdcd4 and eIF4A by TAT-eIF4AVI prevents mice to suffer from CRS-induced anxiety- and depression-like behaviors." (PMID 32203159, 2021). "Our work first reveals that Pdcd4 selectively repressed the translation of variant IIc BDNF mRNA, which is involved in depression." (PMID 32203159, 2021). "Our previous report points that the overexpression of Pdcd4 leads to depressive behavior, and lentivirus packaged siPdcd4 is injected into hippocampus, that provids opportunity for depression therapy." (PMID 34772918, 2021). "Consistently, NCBI GEO database profiles showed that patients with depression had higher Pdcd4 expression in the hippocampus." (PMID 32203159, 2021). "Our previous results indicate that silencing of Pdcd4 expression in hippocampus has antidepressant effect in depressive mice, suggesting siPdcd4 can be applied for depression therapy as an antidepressant." (PMID 34772918, 2021). "Our previous study also emphasized the critical translational mechanism of BDNF in depression, and found Pdcd4 is the key regulator in that." (PMID 34772918, 2021). "Pdcd4 plays a critical role in the pathogenesis of depressive disorder, and thus is a potential target of antidepressant." (PMID 32203159, 2021). "Therefore, Pdcd4 is a new target for depression treatment, and silencing the expression of Pdcd4 in central nervous system provides a theoretical basis for the antidepressant drugs discovery." (PMID 34772918, 2021). "In addition, the inhibitory effect of Pdcd4 on BDNF mRNA translation depends on eIF4A, which extends our understanding of the mechanisms underlying the vital role of mRNA translation in depression regulation." (PMID 32203159, 2021).
depression (continued). "To investigate whether Pdcd4 was involved in CRS-induced depression-like behaviors, we applied the Pdcd4 knockout (KO) mice into the CRS paradigm." (PMID 32203159, 2021). "Animal studies show that blocking Pdcd4 in depression promotes BDNF expression, indicating that Pdcd4 may be a potential anti-depression target." (PMID 33960267, 2021). "Our previous work has shown that CRS could up-regulated the expression of Pdcd4 that contribute to synaptic plasticity impairment and depression-like behavior by inhibiting the expression of BDNF." (PMID 34772918, 2021). "Second, our data provide a novel insight about Pdcd4 in the development of depression." (PMID 32203159, 2021). "We found that Pdcd4 meditated the function of mTORC1-BDNF axis in depression." (PMID 32203159, 2021). "Our findings have provided a novel insight into the role of Pdcd4 in stress-induced emotional disorders, suggesting Pdcd4 might be an effective option for the treatment of depressive disorder." (PMID 32203159, 2021). "Together, our results reveal a distinct role of the tumor suppressor Pdcd4 in regulating neuronal plasticity in depressive disorders, and it might be a potential target for antidepressant treatment." (PMID 32203159, 2021). "In this article, we provide direct evidence that Pdcd4 impairs synaptic plasticity and consequently results in the depression-like behaviors through suppression of BDNF mRNA translation in response to CRS, suggesting Pdcd4 might be a potential target for depression therapy." (PMID 32203159, 2021). "Therefore, Pdcd4 is a typical molecule therapeutic target for depression and silencing Pdcd4 could specifically elevated BDNF expression at translational level." (PMID 34772918, 2021). "Especially, knockout of Pdcd4 directly upregulates BDNF expression at translational level and reverses CRS-induced depression-like behaviors." (PMID 34772918, 2021). "Regardless of the devasting role of neuronal Pdcd4 in chronic restraint stress (CRS)-induced depression, we found microglia Pdcd4 knockout protect mice from LPS-induced depressive-like behaviors." (PMID 38822367, 2024). "To further confirm a direct role of Pdcd4-mediated BDNF-TrkB signaling pathway in CRS-induced emotional disorders, we next investigated whether blockage of BDNF could boost depression in CRS-treated Pdcd4 ncKO mice." (PMID 32203159, 2021). "To address the potential value of Pdcd4 as a target of anti-depressive therapy, we investigated whether knockdown of Pdcd4 with siRNA could prevent or rescue CRS-induced depression- and anxiety-like behaviors in mice." (PMID 32203159, 2021). "In summary, we discovered that microglial Pdcd4 plays a role in LPS-induced depressive behavior, highlighting the various functions of Pdcd4 in nerve cells and brain regions, particularly its immunoregulatory role in the PFC during neuroinflammation-related depression." (PMID 38822367, 2024). "Moreover, over-expression of Pdcd4 in the hippocampus triggered spontaneous depression-like behaviors under the non-stressed conditions in mice, while systemic or neuron-specific knockout of Pdcd4 reverses CRS-induced depression-like behaviors." (PMID 32203159, 2021). "Due to the translational repressor function of Pdcd4, we found its negative role in depression." (PMID 34772918, 2021).
head and neck cancer (5 papers, 2014 to 2025). A primary or metastatic malignant neoplasm affecting the head and neck. "Low PDCD4 level was associated with advanced M category of urinary system cancers (OR 4.87, 95% CI 1.69–14.00) and advanced clinical stage of head and neck cancers (OR 2.30, 95% CI 1.44–3.69)." (PMID 27852288, 2016). "PDCD4 expression was significantly associated with the differentiation status of head and neck cancer (OR 4.25, 95% CI 1.87–9.66) and digestive system cancer (OR 2.87, 95% CI 1.84–4.48)." (PMID 27852288, 2016). "Low PDCD4 expression level was associated with advanced T category of urinary system cancers (OR 4.87, 95% CI 1.69–14.00) and head and neck cancers (OR 2.15, 95% CI 1.10–4.19)." (PMID 27852288, 2016). "Low PDCD4 level was associated with moderately/poorly differentiated head and neck cancers (OR 4.25, 95% CI 1.87–9.66) and digestive system cancers (OR 2.87, 95% CI 1.84–4.48)." (PMID 27852288, 2016). "Down-regulation of PDCD4 expression was associated with unsatisfactory DSS in patients with head and neck cancers (HR: 5.05, 95% CI 1.12–62.50), brain tumors (HR: 15.87, 95% CI 3.62–71.43), and gynecologic cancers (HR: 3.36, 95% CI 1.43–7.81)." (PMID 27852288, 2016). "Low PDCD4 expression was significantly associated with advanced stages of head and neck cancers." (PMID 27852288, 2016). "Furthermore, low PDCD4 expression was associated with advanced stage head and neck cancers and respiratory system cancers." (PMID 27852288, 2016). "Reduced PDCD4 was usually found in aggressive head and neck cancers." (PMID 27533461, 2016). "There was no obvious evidence for an association between PDCD4 expression and the N category of head and neck cancers, respiratory system cancers, and digestive system cancers." (PMID 27852288, 2016). "Promotes EMT and invasiveness in head and neck cancers by targeting PTEN and PDCD4." (PMID 40895189, 2025).
thyroid cancer (5 papers, 2017 to 2025). "Collectively, these data indicate that sustained downregulation of PDCD4 during thyroid cancer dedifferentiation is associated with enhanced M2‐like macrophage infiltration and immunosuppressive remodeling, potentially driving tumor progression." (PMID 40908584, 2025). "Further, hsa-miR-183 was found to play a role in thyroid cancer tumorigenesis, by targeting programmed cell death 4 (PDCD4)." (PMID 38672402, 2024). "Western blotting (WB) analysis across thyroid cancer cell lines showed that PDCD4 expression was markedly reduced or absent in ATC cell lines (BHT101, ACT1, 8305C, BPC (mouse‐derived) compared to DTC cell lines (TPC‐1, B‐CPAP, K1, KTC‐1)." (PMID 40908584, 2025).
tongue cancer (5 papers, 2017 to 2022). A malignant neoplasm affecting the tongue. "In Zinc deficiency esophagus and tongue cancers, oncogenic miR-31 overexpression was accompanied by down-regulation of their respective tumor-suppressor targets PPP2R2A and PDCD4." (PMID 29145896, 2017). "Upregulation of miR-155 by targeting PDCD4 is involved in the progression of tongue cancer." (PMID 35402235, 2022). "In tongue cancer, miR-155 has been found to target Pdcd4 transcript and inhibit its expression." (PMID 35402235, 2022). "Also, a feedback loop between the OncomiR miR-155 and programmed cell death 4 (Pdcd4) with the activation of protein 1 modulates the miR-155 expression and tumorigenesis in tongue cancer." (PMID 36071981, 2022). "In addition, miR‐155 has been demonstrated to directly inhibit the expression of PDCD4 and further regulate cell proliferation in Tongue cancer." (PMID 33769664, 2021).
brain tumor (4 papers, 2010 to 2022). "Furthermore, RVG-modified exosomes enriched with miR-21 inhibitors effectively induced the expression of target genes PTEN and PDCD4 in recipient cells and reduced the brain tumor size." (PMID 36497090, 2022). "PDCD4 could inactivate nuclear NF-κB (p65) without interfering the activation status of upstream IKKα/β and IκBα in brain tumor." (PMID 27533461, 2016).
carcinoid (4 papers, 2009 to 2022). "A study on Bon-1 carcinoid cells showed that PDCD4 not only suppressed the transcription of the mitosis-promoting factor cyclin-dependent kinase 1(CDK1)/cdc2, but also decreased the expression of CDK4/6." (PMID 19480673, 2009). "There are a multitude of studies examining the expression of PDCD4 in cancer or carcinoid cells." (PMID 35847932, 2022). "Overexpression of Pdcd4 resulted in inhibition of carcinoid cell proliferation." (PMID 19728867, 2009). "One such down-regulated protein is carbonic anhydrase (CA) II, which is required for a high bicarbonate flux needed metabolically for proliferation in some carcinoid cells and decreased translation of CAII in Bon-1 and HEK293 cells by PDCD4 inhibits cell growth." (PMID 35847932, 2022).
endometrial cancer (4 papers, 2021 to 2025). Primary or metastatic malignant neoplasm involving the endometrium (mucous membrane that lines the endometrial cavity). "Ubiquitination and proteasome degradation of PDCD4 through E3 ubiquitin ligase has been described in ovarian and endometrial cancer cells." (PMID 36552834, 2022). "Additionally, miR-21 has been clinically applied in gynecological cancers, including ovarian, cervical, and endometrial cancers, as it regulates the downstream target programmed cell death 4 (PDCD4)." (PMID 40508066, 2025). "In fact, a previous study reported that the ubiquitination and degradation of PDCD4 could increase the migration and invasion of ovarian and endometrial cancer cells." (PMID 36552834, 2022).
endothelial dysfunction (4 papers, 2022 to 2025). In vascular diseases, endothelial dysfunction is a systemic pathological state of the endothelium (the inner lining of blood vessels) and can be broadly defined as an imbalance between vasodilating and vasoconstricting substances produced by (or acting on) the endothelium. "This study provides more evidence that PDCD4 is involved in the pathophysiology of AF, which has important consequences for its function in endothelial dysfunction, chronic inflammation, and atrial fibrosis." (PMID 40766329, 2025). "The EVs from LSW-stimulated VSMCs attenuated oxLDL-induced endothelial dysfunction by targeting the PDCD4 expression in HVUECs." (PMID 36296612, 2022). "Oxidized low-density lipoprotein (oxLDL) was applied to induce endothelial dysfunction in HUVECs; oxLDL-induced endothelial dysfunction in HUVECs was attenuated by PDCD4 knockout or LEVs incubation." (PMID 36296612, 2022). "Future studies are necessary to examine whether TSA can target PDCD4-related pathways in AF, particularly those involved in fibrosis and endothelial dysfunction." (PMID 40766329, 2025). "The antihypertensive tripeptide Leu-Ser-Trp (LSW) could increase miRNA-145 loading in VSMC-derived EVs and attenuated ox-LDL-induced endothelial dysfunction via miRNA-145 delivery, which was internalized into ECs and downregulated PDCD4 (programmed cell death protein 4) expression." (PMID 36937921, 2023). "However, it is worth exploring whether the antagonistic effect of LEVs on oxLDL-induced endothelial dysfunction stems from PDCD4." (PMID 36296612, 2022).
ischemic stroke (4 papers, 2017 to 2025). A stroke disorder caused by obstruction of blood flow to the brain, due to thrombotic (local blood clot formation) or embolic (due to a blood clot or other material traveling from another site) event. "Pterostilbene, also a phenolic compound in dragon’s blood, showed a protective function on both neurons and cerebral tissues against ischemic stroke injuries by modulating micro-ribonucleic acid (miR)-21-5p/Programmed Cell Death Protein 4 (PDCD4) axis in vivo and in vitro." (PMID 36615573, 2023). "In addition, miR‐21 shows potent neuroprotective effects after spinal cord injury, alleviates blood‐brain barrier disruption in ischemic stroke, and promotes neurite outgrowth by regulating programmed cell death protein 4 (PDCD4)." (PMID 35716062, 2022). "To investigate the role of PDCD4 and GVI PLA2 in ischemic stroke, we performed Western blot analysis on cortical tissue collected at 1, 3, and 7 d post‐MCAO." (PMID 40271828, 2025).